PDX1 (pancreatic and duodenal homeobox 1)
Diseases named in the same sentence as PDX1 in open-access papers (continued):
Sharing a sentence is not in itself a finding about the gene and the disease.
diabetes (continued). "The homeodomain transcription factor IPF1/PDX1 exerts a dual role in the pancreas; Ipf1/Pdx1 global null mutants fail to develop a pancreas whereas conditional inactivation of Ipf1/Pdx1 in β-cells leads to impaired β-cell function and diabetes." (PMID 18036209, 2007). "Mouse models of Pdx1 mutations also highlight species differences: while homozygous loss leads to pancreatic agenesis, heterozygous mice develop only mild glucose intolerance rather than overt diabetes, in contrast to the progressive β-cell failure characteristic of PDX1-MODY in humans." (PMID 41199860, 2025). "Additionally, one study found that adding a dominant-negative form of JNK prevented oxidative stress-induced Pdx-1 translocation, which in turn prevented β-cell dysfunction in diabetes." (PMID 39996734, 2025). "MEG3 is downregulated in the islets and blood of individuals with diabetes, and in a murine β-cell line (MIN6), MEG3 seems to regulate insulin synthesis and secretion since its absence reduced the expression of key factors for β-cell function (PDX-1 and MAFA), decreasing insulin synthesis." (PMID 38326874, 2024). "Additionally, we attempted to dissect the mechanisms by which EGCG mitigated β-cell disturbances, and found that EGCG inhibited experimental diabetes triggered by a high-sucrose-high-fat (HSHF) diet and streptozotocin (STZ) administration by increasing upregulating pancreatic PDX-1 and MafA." (PMID 35656076, 2022). "Additionally, it has been shown that such a reduction in insulin biosynthesis and secretion together with a reduction in PDX-1 and MafA is preserved by mitigating pancreatic β-cell failure with insulin preparation or SGLT2 inhibitors, especially in the early stage of diabetes mellitus." (PMID 35453568, 2022). "However, as previously stated, some 35-week-old Pdx1.tTA mice exhibited high blood glucose levels up to 26.6 mmol/L (data not shown) indicating that aging is able to trigger diabetes development in Pdx1+/− animals." (PMID 31682591, 2020). "Other attempts to deliver combinations of transcription factors, such as Pdx1 and Neurogenin 3 (Ngn3), improved the blood glucose levels of diabetic mice, but could not fully cure diabetes." (PMID 33023100, 2020). "The effect of CPP extract on various genes such as Pdx-1, Ins-1, ngn-3, GLUT-4, and IRS-1 in insulin signaling pathway and Traf-4, Traf-6, and Mapk-8 in MAPK downstream JNK cascade was examined through qRT-PCR to access the core molecular mechanism involved in CPP-induced recovery of diabetes." (PMID 32256963, 2020). "Thus, while both PDX1 and MAFA have been demonstrated to play essential roles in α-to-β reprogramming, identifying efficient methods to generate surrogate β cells, which will lead to the establishment of regenerative therapies for people with diabetes, still remains a challenge." (PMID 36496541, 2022). "Thus, STAT3 modulation and β-cell ablation nonadditively enhance α-to-β reprogramming induced by PDX1, which may lead to the establishment of cell therapies for curing diabetes." (PMID 36496541, 2022). "In MafA-/- mice, insulin 1, insulin 2, PDX-1, neurogenic differentiation (NeuroD) and glucose transporter 2 (GLUT2) amounts are reduced, and glucose, arginine and KCl-induced insulin secretion are remarkably altered Thus, PDX-1 and MafA may be important factors in diabetes therapy." (PMID 35656076, 2022). "However, PDX1 treatment was not effective in restoring a functional β-cell population and in rescuing diabetes in mice, which could be due to several aspects." (PMID 35186929, 2022). "PDX1 treatment increased islet area and the percentage of central islets compared to untreated STZ mice but did not revert diabetes." (PMID 35186929, 2022). "Most studies have reported reduced expression of MafA and PDX-1 in type 2 diabetes, but no study was found to clarify the effects of N. sativa on MafA and PDX-1 changes in STZ-induced diabetes model (type 1 diabetes)." (PMID 36109786, 2022).
diabetes (continued). "Furthermore, also regardless of HNF4A mutation carrier status or diabetes status, the S7 cells displayed the same GSIS kinetics, the same ultrastructural features and the same levels of proteomics-based protein markers of a mature β-cell, including INS, PDX1, NKX6.1, MAFA, GLUT2, UCN3 and others." (PMID 28684784, 2017). "Infants with neonatal diabetes have also been investigated for gene defects for diabetes, such as PLAGL-1 (ZAC), glucokinase and PDX-1 (IPF-1) genes, with negative results." (PMID 26761945, 2016). "Moreover, human islets from donors with and without diabetes treated with osteocalcin showed a reduced nuclear FOXO1 and an increase in nuclear PDX1." (PMID 40585255, 2025). "While Pdx1+/− mice were found glucose intolerant without progressing to diabetes, additional challenge of β-cell function by IKK/NF-κB inhibition promoted rapid diabetes development showing hyperglycaemia, hypoinsulinemia and loss of β-cell mass." (PMID 31682591, 2020). "For instance, adenovirus-mediated delivery of Pdx1 or Ngn3 was shown to induce insulin expression by the liver, whereas AAV-mediated overexpression of the same TFs did not result into insulin production or correction of diabetes in mice." (PMID 28193997, 2017).
pancreatic cancer (217 papers, 2010 to 2026). "UN-KC-6141 cells were derived from a pancreatic tumor of a KrasG12D;Pdx1-Cre (KC) mouse engineered to express gene mutations commonly observed in pancreatic cancer patients." (PMID 40430543, 2025). "There have been at least four genome-wide significant variants located in PDX1 or PLUTO found to be associated with fasting blood glucose or pancreatic cancer." (PMID 34329319, 2021). "When studying the expression of motility genes, we found changes in the expression of genes associated with the TGF-β signaling pathway in pancreatic cancer cells with ectopic expression of PDX1." (PMID 34503200, 2021). "Next, we generated KrasLSL-G12D/+;Jag1flox/flox;Pdx1-Cre mice (hereafter referred to as KJC) to determine the impact of Jag1 loss on KrasG12D-induced pancreatic cancer initiation and progression." (PMID 33268505, 2021). "Ectopic expression of PDX1 in pancreatic cancer cells showed decreased expression levels of genes associated with increased cell migration capability, as well as increased expression of genes negatively affecting cell motility." (PMID 34503200, 2021). "Although to our knowledge, our study is the first to observe an interaction between obesity and PDX1 rs9581943, polymorphisms of other genes have been reported to interact with obesity to influence pancreatic cancer risk." (PMID 32456644, 2020). "In the commonly used LSL-KrasG12D/+; Pdx-1-Cre (KC) mouse model with an activating Kras mutation targeted to the pancreas, pancreatitis accelerates the development of pancreatic cancer." (PMID 33396954, 2020). "Additional analyses showed two significant gene-environment interactions (between poor oral hygiene and NR5A2 rs2816938 and between obesity and PDX1 rs9581943) on the risk of pancreatic cancer." (PMID 32456644, 2020). "We conducted gene-environment analyses with four SNPs (NR5A2 rs2816938, MYC rs10094872, PDX1 rs9581943 and a chromosome 13q22 SNP, rs4885093) significantly associated with pancreatic cancer risk." (PMID 32456644, 2020). "BMI ≧ 27 was associated with an increased pancreatic cancer risk only among individuals with the PDX1 rs9581943 GA or AA genotype (OR = 2.99, 95% CI: 1.89–4.72) but not among those with the GG genotype (OR = 1.13, 95% CI: 0.63–2.00)." (PMID 32456644, 2020). "In fact, some studies have shown that conditional loss of SMAD4 or TGFBR2 in Pdx1-Cre/LSL-KRas mice develop advanced aggressive pancreatic cancer." (PMID 29156578, 2017). "NNK exposure to KC (LSL-KrasG12D/+;Pdx-1-Cre) mice, which are predisposed to spontaneous pancreatic intraepithelial neoplasia (PanIN) and pancreatic cancer development, resulted in increased mean pancreatic weights compared to mice receiving simultaneous NNK and broad-spectrum antibiotic treatment." (PMID 40104059, 2025). "In addition, our results showed two significant gene-environment interactions (between poor oral hygiene and NR5A2 rs2816938 and between obesity and PDX1 rs9581943) on the risk of pancreatic cancer." (PMID 32456644, 2020). "Interestingly, we also observed prominent MAPK activity in the stromal cells of Pdx1-Cre;HIF2dPA pancreata, a phenomenon also reported in fibrosis associated to pancreas cancer formation." (PMID 30209343, 2018). "Common low penetrance variants in gene loci including ABO, TERT and PDX1 that contribute to pancreatic cancer risk have been identified through genome-wide association studies, but much of the familial clustering of pancreatic cancer remains unexplained." (PMID 28881607, 2017).
pancreatic cancer (continued). "This increased pancreatic cancer predisposition was not limited to invasive tumors; the number of PanINs observed in 6-week-old Pdx1-Cre, KrasG12D/+, Lkb1flox/+ (KLC) mice was significantly increased when compared with Pdx1-Cre, KrasG12D/+ (KC) mice (P = .007)." (PMID 20452353, 2010). "Finally, in order to establish the pivotal role of Nupr1 in the repression of HoCC in vivo, we investigated whether Nupr1-deficiency resulted in more cell-in-cells in pancreatic tumours developed by the Pdx1-creER; LSL-KRASG12D; INK4A/ARFfl/fl mice." (PMID 22821859, 2012). "Pancreatic tumors specifically feature three targets: pancreatic and duodenal homeobox 1 (PDX1), KRAS protooncogene GTPase (KRAS), and tumor necrosis factor (TNF)." (PMID 41041638, 2025). "Mouse pancreatic tumor cells isolated from Trp53em4(R172H)Krasem4(LSL−G12D Tg(Pdx1-cre)Smoc (KPC) genetically engineered mice were injected into the sciatic nerve." (PMID 40119353, 2025). "The Pdx1-CreLSL-KrasG12DTp53R172H/+ (KPC) model accelerates the development of invasive pancreas cancer, mimicking human disease dynamics." (PMID 40829173, 2025). "GEMMs incorporating Smad4 deletion alongside KrasG12D expression, such as Pdx1-CreLSL-KrasG12DSmad4lox/lox, exhibit robust tumor progression and desmoplastic stromal responses, hallmarks of human pancreas cancer." (PMID 40829173, 2025). "For instance, a study on pancreatic cancer utilized qRT-PCR to detect PDX1 transcripts in patient serum and reported significantly elevated PDX1 levels in pancreatic cancer patients compared to healthy controls." (PMID 40405977, 2025).
pancreatic cancer (continued). "To further support these observations, we induced SGs formation in pancreatic cancer cells obtained from Pdx1-cre;LSL-KrasG12D/INK4a/Arf’fl/fl/NUPR1+/+ or Pdx1-cre;LSL-KrasG12D/INK4a/Arf’fl/fl/NUPR1-/- mice." (PMID 38360999, 2024). "HMGCL protein level is high in pancreatic cancer in mice (Pdx1-Cre; lox-stop-lox-KrasG12D/+; Ink4a/Arflox/lox)." (PMID 37958351, 2023). "Pancreatic expression of Hmgcr is upregulated in a murine spontaneous pancreatic cancer model (Pdx1-Cre; lox-stop-lox-KrasG12D/+; Ink4a/Arflox/lox), as well as in pancreatic cancer patients." (PMID 37958351, 2023). "Acetyl-CoA abundance is elevated in acinar cells of the pancreatic cancer mouse model called KC (Pdx1-Cre; lox-stop-lox-KrasG12D/+), and acetyl-CoA in the cholesterol biosynthesis pathway supports acinar-to-ductal metaplasia (ADM) formation." (PMID 37958351, 2023). "To generate spontaneous pancreatic tumors in these mice, we crossbred Pdx1-Cre/R26LSL-LSIY with KrasLSL-G12D/+Tp53LSL-R172H/+ mice to generate KPC-LSIY mice as well as with Pdx1-Cre mice to generate conventional KPC mice." (PMID 37072485, 2023). "Pancreas-specific KrasG12D mice sufficiently developed pancreatic intraepithelial neoplasia using a Pdx1 promoter, and active Akt1 cooperated with KrasG12D to accelerate pancreatic carcinoma onset and progression." (PMID 37247123, 2023). "We first aimed to query the cachexia-inducing properties of T4- and T3-KPC (KrasLSL.G12D/+; p53LSL.R172H/+; Pdx1-Cre) pancreatic cancer cells in vitro." (PMID 34874916, 2022). "We next investigated sympathetic innervation in the LSL-KrasG12D/+; Cdkn2a (Ink4a/Arf)lox/lox; Pdx1-Cre (KIC) mouse model of pancreatic cancer." (PMID 35418199, 2022). "In this study, and with animal models, we confirmed the strong association of elevated levels of endotoxin with the malignant transformation of pancreatic cancer in a Pdx1-Kras background." (PMID 35326559, 2022). "The upregulation of miR-1273 was detected in the KrasG12D Pdx1-Cre pancreatic cancer mouse model compared with the control mice." (PMID 35647303, 2022).